CDK9 (cyclin dependent kinase 9)
Diseases named in the same sentence as CDK9 in open-access papers (continued):
Sharing a sentence is not in itself a finding about the gene and the disease.
neuroblastoma (12 papers, 2015 to 2025). Neuroblastoma (NB) is the most common solid, extracranial childhood tumor. "The CDK9/2 inhibitor CYC065 that selectively targets MYCN-amplified neuroblastoma in vitro, caused growth arrest after 48 h and cell death in WT cultures upon prolonged treatment for 5 days." (PMID 39740515, 2025). "Deregulation of CDK9/cyclin T1 activity is essentially associated with its overexpression in several B and T-cell lymphomas, as well as in neuroblastoma, primary neuroectodermal tumor, rhabdomyosarcoma and prostate cancer." (PMID 25625291, 2015). "Used at low concentrations, Dinaciclib is a broad CDK inhibitor (CDK1, 2, 5, and 9), but its antagonistic effect on CDK2 and CDK9 has been attributed to its ability to suppress neuroblastoma cell proliferation." (PMID 33796454, 2021). "CYC065, used together with temozolomide, a reference therapy for relapsed neuroblastoma, caused long-term suppression of neuroblastoma growth in vivo, highlighting the clinical potential of CDK9/2 inhibition in the treatment of MYCN-amplified neuroblastoma." (PMID 33016930, 2020). "In addition to hematological malignancies where Mcl-1 is the major target, Myc-driven diseases such as neuroblastoma are a trending area for the development of CDK9 inhibitors, with a few compounds being actively tested in the clinic." (PMID 35383271, 2022). "Indeed, specific subgroups of patients are more dependent on CDK7 (triple-negative breast cancer) and/or CDK9 (MYC-driven neuroblastoma)." (PMID 34344865, 2021). "Moreover, CDK9 expression levels have been found to correlate with the differentiation grade of neuroblastoma and primary neuroectodermal tumours." (PMID 25625291, 2015). "However, when we combined BTYNB with AZD4573, a highly selective CDK9 inhibitor that has recently been shown to induce apoptosis in hematologic cancer, we observed a synergistic effect between both inhibitors, significantly decreasing cell proliferation in each neuroblastoma cell line tested." (PMID 33796454, 2021). "a potent, multiple- cyclin-dependent kinase (CDK) inhibitor has been shown to suppress neuroblastoma growth by inhibiting CDK2 and CDK9 activity." (PMID 33796454, 2021). "Here, we show that CYC065 (fadraciclib), a clinical inhibitor of CDK9 and CDK2, selectively targeted MYCN-amplified neuroblastoma via multiple mechanisms." (PMID 33016930, 2020). "In this study, we found that dinaciclib significantly inhibited both anchorage-dependent and independent growth in a panel of neuroblastoma cells by abrogating CDK2 and CDK9 activity." (PMID 27378523, 2016). "A clinical inhibitor of Cdk9 and Cdk2, CYC065, can hinder the transcriptional activation of N-Myc by inhibiting the Cdk9 in P-TEFb complex, realizing the therapeutic effect on MYCN-amplified neuroblastoma." (PMID 34658888, 2021). "Next we attempted to determine whether CDK2 and CDK9 inhibition, when combined with IGF2BP1 inhibition, would have an additive effect on neuroblastoma cell replication." (PMID 33796454, 2021).
bladder cancer (11 papers, 2019 to 2023). "CDK9 is overexpressed in bladder cancer and correlates with favorable clinical features and longer patient survival." (PMID 36374405, 2023). "In our recent study, CDK9 was overexpressed in all clinical stages of bladder cancer, while its levels decreased in line with grade and stage." (PMID 36374405, 2023). "This network module has 6 putative bladder cancer drivers including PPARG and CDK9 and the known bladder cancer driver ERBB3." (PMID 35035776, 2022). "The presented results show that although CDK9 is overexpressed in all stages and grades of bladder cancer when compared to normal bladder tissue, its expression decreases in line with higher grade and stage." (PMID 35326643, 2022). "We explored the relevance of CDK9 expression in human urothelial carcinoma by comparing normal urothelial mucosa and urothelial carcinoma of bladder cancer patients." (PMID 35326643, 2022). "In this study, we primarily identified a novel lncRNA termed GAS6‐AS2, and our research proved that GAS6‐AS2 contributed to proliferation and metastasis of bladder cancer cells via the GAS6‐AS2/miR‐298/CDK9 axis." (PMID 30394665, 2019). "We found knockdown of CDK9 antagonized both proliferation and metastatic abilities of bladder cancer cells, which indicated that CDK9 was an important effector in GAS6‐AS2/miR‐298 axis." (PMID 30394665, 2019). "CDK9 staining intensity was measured in normal tissue and bladder cancer samples." (PMID 36374405, 2023). "Contrary to results from other malignancies, CDK9′s role in bladder cancer seems different." (PMID 35326643, 2022). "With the Kaplan–Meier estimator, the results indicate that CDK9 may predict a good prognosis in patients with bladder cancer." (PMID 35326643, 2022). "LncRNA GAS6-AS2 promotes the proliferation and metastasis of bladder cancer cells with a mechanism in which GAS6-AS2 may function as a ceRNA by directly sponging miR-298 to regulate the CDK9 expression." (PMID 34049287, 2021). "In conclusion, our results demonstrated that GAS6‐AS2 could promote proliferation and metastasis of bladder cancer cells via regulating GAS6‐AS2/miR‐298/CDK9 axis." (PMID 30394665, 2019). "It seems that CDK9 not only regulates the expression of anti-apoptotic genes, leading to longer survival of cancer cells, it also facilitates DNA repair, preventing the build-up of genomic instability, crucial in the initiation and progression of bladder cancer." (PMID 35326643, 2022). "In this study, we firstly reported a novel lncRNAs termed GAS6‐AS2, promoted proliferation and metastasis of bladder cancer cells via GAS6‐AS2/miR‐298/CDK9 axis, which might serve as a potential biomarker for clinical diagnosis and treatment of bladder cancers." (PMID 30394665, 2019). "The long non-coding RNA GAS6-AS2 promotes bladder cancer proliferation and metastasis through the GAS6-AS2/miR-298/CDK9 axis." (PMID 34906173, 2021). "Nevertheless, to this day, no clinical trials regarding the use of CDK9 inhibitors in bladder cancer have been conducted." (PMID 36374405, 2023). "Similarly, lncRNA GAS6-AS2 stimulated bladder cancer proliferation and metastasis via GAS6-AS2/miR-298/CDK9 signaling." (PMID 34852711, 2022).
triple-negative breast carcinoma (10 papers, 2016 to 2026). An invasive breast carcinoma which is negative for expression of estrogen receptor (ER), progesterone receptor (PR), and human epidermal growth factor receptor 2 (HER2). "Targeting CDK9 is considered as an effective treatment for many cancers, such as triple negative breast cancer, small cell lung cancer and colorectal cancer." (PMID 40636359, 2025). "Studies have found that potent and selective CDK9 inhibitors target transcriptional regulation in triple-negative breast cancer." (PMID 39445026, 2024).
AIDS (9 papers, 2012 to 2023). A syndrome resulting from the acquired deficiency of cellular immunity caused by the human immunodeficiency virus (HIV). "In addition, it has been suggested that deregulation of CDK9 activity and CDK9-interacting proteins are associated with several other human diseases, including acquired immunodeficiency syndrome (AIDS) or cardiac hypertrophy." (PMID 22571657, 2012). "CDK9 inhibitors that are effective in the treatment of AIDS and cancer must be taken long-term and must have high specificity." (PMID 36378653, 2022). "Because of the high potential of CDK9 inhibitors as therapeutic agents for various diseases including HIV/AIDS and cancer, many new CDK9 inhibitors have been developed." (PMID 32075058, 2020). "Because of CDK9′s potential as a therapeutic target in AIDS, cancer, inflammation, and cardiomyophathy it is important to understand the consequences of CDK9 inhibition." (PMID 24886624, 2014). "Understanding the effects of CDK9 inhibition on gene expression over time is of considerable interest because it is a potential therapeutic target in a number of diseases including AIDS, certain cancers, inflammatory processes and hypertrophic cardiomyopathy." (PMID 22458775, 2012). "Since inhibition of CDK9 activity is being explored as a therapeutic avenue in a number of diseases including AIDS, cancer, cardiac myopathies and inflammatory processes, it is important to examine the time dependent consequences of CDK9 inhibition on gene expression." (PMID 22458775, 2012).
diffuse large B-cell lymphoma (9 papers, 2017 to 2026). "In diffuse large B-cell lymphoma, CDK9 inhibitors including CDKI-73 frequently induce histone 3 lysine 27 trimethylation, which is associated with tumor progression." (PMID 34065376, 2021). "In addition to the combination with BET inhibitors, the literature has documented the concurrent application of the CDK9 inhibitor AZD4573 in conjunction with PIM kinase or PI3K inhibitors in the context of diffuse large B-cell lymphoma (DLBCL) and primary lymphoma cells." (PMID 39838405, 2025). "We have demonstrated that AZ5576, a selective CDK9-inhibitor, led to rapid downmodulation of MYC and Mcl-1 in diffuse large B-cell lymphoma (DBLCL), accompanied by a shutdown of the MYC transcriptional program and apoptosis." (PMID 36998071, 2023). "We did not test the CDK9 inhibitor dinaciclib in this study, as previous studies in diffuse large B-cell lymphoma (DLBCL) have been reported." (PMID 29291023, 2017). "The non-selective CDK9 inhibitor CDKI-73 proved anti-proliferative and pro-apoptotic capacity in chronic lymphoblastic leukemia (CLL), diffuse large B-cell lymphoma, ALL and AML cells, as well as in animal models." (PMID 34065376, 2021).
HIV-1 infection (9 papers, 2011 to 2024). The type species of lentivirus and the etiologic agent of acquired immunodeficiency syndrome (AIDS). "CDK9 (cyclin-dependent kinase 9) plays a significant role in numerous pathological conditions, such as HIV-1 infection and cancer." (PMID 38808256, 2024). "It inhibited HIV-1 infection with an IC50 = 0.2 μM and could disrupt the Tat-TAR RNA and Tat-CDK9 interactions." (PMID 37298089, 2023). "Immunofluorescence confirmed that a significant fraction of the CCNT1 subunit of P-TEFb was localized to the cytoplasm, consistent with a previous observation that CCNT1 and CDK9 are detected in the cytoplasm in unstimulated resting memory CD4+ T cells, the target immune cells of HIV-1 infection." (PMID 29845934, 2018). "While this is not the only Cdk9 residue to be phosphorylated, it certainly is critical for P-TEFb function, and it is likely that low levels of Thr186-phosphorylated Cdk9 may contribute to the refractoriness of resting CD4+ T cells and monocytes to HIV-1 infection and replication." (PMID 24832049, 2012).
mantle cell lymphoma (9 papers, 2019 to 2026). Mantle cell lymphoma is a rare form of malignant non-Hodgkin lymphoma affecting B lymphocytes in the lymph nodes in a region called the ``mantle zone''. "Targeting cyclin-dependent kinase-9 (CDK9) in mantle cell lymphoma is also being explored as a means of overcoming treatment resistance in MCL." (PMID 38792015, 2024). "In particular, flavopiridol was a nonselective CDK9 inhibitor (CDK9/cyclin T1 Ki = 3 nM) which showed in vivo activity in hematologic malignancies (e.g., mantle cell lymphoma, CLL) but was halted due to high toxicity." (PMID 38172923, 2024). "PRT2527: PRT2527 is a selective and potent cyclin-dependent kinase 9 inhibitor that exhibits antiproliferative and proapoptotic activity in DLBCL, CLL, and mantle cell lymphoma (MCL) cell lines." (PMID 39796724, 2024).
viral infection (9 papers, 2006 to 2024). "To further investigate kinases involved in STAT2 activation at the early stage of viral infection, we constructed CDK9 or MAPK12 knockdown A549 cells using specific shRNAs, respectively." (PMID 36148221, 2022). "Understanding the requirements of CDK9 for viral infection and how viral infection alters pol II CTD phosphorylation patterns not only advances our knowledge of viral pathogenesis but also provides potential new anti‐viral drug targets." (PMID 27398404, 2016). "Release of CDK9 from the 7SK snRNP and resulting transcription of P-TEFb-dependent genes greatly impacts mammalian cell survival during genotoxic stress and interferon responses during viral infection." (PMID 39316591, 2024). "Our CDK9 development strategy for targeting the specific local structure of P-TEFb and viral protein complexes may be useful for the development of novel therapeutics against other viral diseases involving P-TEFb." (PMID 36378653, 2022). "The increased association of Cyclin T1 with CDK9 leads to elevated Cyclin T1/P-TEFb kinase activity, and this appears to be utilized by the HIV-1 Tat protein to stimulate viral LTR-directed transcription as suggested by our results with Tat+ reporter virus infection." (PMID 17014716, 2006). "During the process of viral infection, NF-κB RelA traffics to the nucleus and interacts with BRD4, CDK9 and other components of the positive transcription elongation factor (p-TEFb)." (PMID 33799525, 2021). "In particular, the activity of CDK9 is crucial for the course of HSV, HCMV, EBV, HIV, HTLV, HAdV, DENV, and KSHV virus infection." (PMID 27398404, 2016). "Chiefly, Brd4 regulates CDK9 and RNAP II phosphorylation during viral infection." (PMID 27764245, 2016).
colorectal cancer (8 papers, 2019 to 2025). A primary or metastatic malignant neoplasm that affects the colon or rectum. "Functionally, high expression of FGFR1 has been shown to be associated with increased proliferation and invasion of colorectal cancer cells; MYO6 is known to be an oncogene in CRC, while CDK9 has been used as a potential target for the treatment of CRC." (PMID 38877540, 2024). "In order to investigate the CDK9 expression level in normal and carcinogenic colorectal tissues, we performed immunohistochemical staining using a monoclonal CDK9 antibody on paraffin-embedded adjacent-normal tissue of colorectal cancer patients." (PMID 36979907, 2023). "CDK9 was highly expressed in colorectal cancer tissues and patients with high expression showed a tendency towards prolonged survival." (PMID 36979907, 2023). "In this study, we demonstrated the overexpression of CDK9 in colorectal cancer tissue compared to normal colon epithelia." (PMID 36979907, 2023). "Given its potency, the combination of CDK9 inhibition by Dinaciclib and izTRAIL treatment appears to be an exceptionally promising approach in colorectal cancer therapy." (PMID 36979907, 2023). "Our research demonstrated that the antitumor activity of izTRAIL used in colorectal cancer is substantially enhanced by CDK9 inhibition." (PMID 36979907, 2023). "In this study, we investigated the role of CDK9 in colorectal cancer as a prognostic marker and its potential via combination with TRAIL agent as a novel therapeutic target." (PMID 36979907, 2023). "First, we determined the relevance of CDK9 expression by comparing normal and cancer tissue samples of colorectal cancer patients." (PMID 36979907, 2023). "The clinical relevance of CDK9 overexpression in colorectal cancer samples is yet to be determined as it is unclear if CDK9 acts as a tumor promotor in colorectal cancer or if the overexpression of CDK9 is a consequence of the cancer genome." (PMID 36979907, 2023). "In this work, we investigated the role of CDK9 in colorectal cancer." (PMID 36979907, 2023). "Thus, further investigations regarding the oncogenic potential of CDK9 in colorectal cancer are warranted." (PMID 36979907, 2023). "Strong immunoreactivity for CDK9 was also found in five colorectal cancer cell lines." (PMID 36979907, 2023). "Moreover, CDK9 inhibition by Dinaciclib resulted in markedly decreased colorectal cancer cell viability and profoundly enhanced TRAIL-mediated apoptosis of resistant colorectal cancer cells via suppression of short-living anti-apoptotic proteins Mcl-1 and c-FLIP." (PMID 36979907, 2023). "Thus, a significantly higher CDK9 expression could be detected in colorectal carcinoma tissue compared to normal tissue." (PMID 36979907, 2023). "We randomly chose 40 colorectal cancer (CRC) patients from our cohort and compared CDK9 expression levels in normal and cancerous colorectal tissues." (PMID 36979907, 2023). "Overall, we identified CDK9 as a prognostic marker and combined CDK9 inhibition and TRAIL as a novel and promising therapeutic approaches for colorectal cancer." (PMID 36979907, 2023). "Based on the findings, CDK9 inhibition represents a promising therapeutic approach and CDKI‐73 is a promising drug candidate for treating colorectal cancer." (PMID 31398271, 2019). "Thus, CDK9 inhibition in combination with TRAIL is a novel, promising therapeutic strategy for colorectal cancer." (PMID 36979907, 2023). "In summary, we could show that CDK9 is overexpressed in colorectal cancer tissues and CDK9 inhibition facilitates izTRAIL mediated apoptosis via downregulation of the short-lived anti-apoptotic proteins Mcl-l and c-FLIP in colorectal cancer cells." (PMID 36979907, 2023).